CXCL10 (C-X-C motif chemokine ligand 10)
Diseases named in the same sentence as CXCL10 in open-access papers (continued):
Sharing a sentence is not in itself a finding about the gene and the disease.
Cirrhosis (28 papers, 2012 to 2025). A chronic disorder of the liver in which liver tissue becomes scarred and is partially replaced by regenerative nodules and fibrotic tissue resulting in loss of liver function. "However, two chemokine ligands, i.e. CXCL9 and CXCL10, were up-regulated, and such an up-regulation was previously associated with liver injury, e.g., cirrhosis and HCC." (PMID 38528259, 2024). "Consistently, we found that increased CD68 (human monocyte lineage/macrophages marker) and CXCL10 staining in livers of HBV-infection-induced hepatic cirrhosis patients compared with normal liver." (PMID 32641985, 2020). "Excluding CCL-11, higher levels of chemokines CCL-3, CCL-4, CCL-5, CXCL-8, and CXCL-10 were observed in compensated cirrhosis patients compared to fibrotic and decompensated cirrhosis patients." (PMID 29977152, 2018). "Importantly, our study identified CXCL5, CXCL9, and CXCL10 as universal HCC markers, independent from underlying etiology of cirrhosis." (PMID 36982370, 2023). "In addition, CXCL9, CXCL10, and CXCL11 are related to the migration of TRAIL CD56+bright NK cells that promote liver injury to the liver in chronic hepatitis B-associated cirrhosis." (PMID 36504808, 2022). "Because we hypothesize that in decompensated cirrhosis the source of CXCL-10 is NPCs, this could partially explain the higher levels seen in the nonresponders." (PMID 28584852, 2017). "We found that in patients with decompensated cirrhosis, elevated baseline CXCL-10 was associated with nonresponse to DAAs." (PMID 28584852, 2017). "Baseline CXCL-10 is a simple test that could predict response to therapy in the majority of patients with decompensated cirrhosis and allow an extended duration of treatment in patients with higher levels." (PMID 28584852, 2017). "HCV-cirrhosis was strongly associated with interferon-associated CXCL10 but not IFN-γ." (PMID 36230823, 2022). "In fact, prior work in cirrhosis showed that higher CXCL9 levels predict poorer survival, supporting our findings that CXCL9 and CXCL10 better capture the injurious immune milieu in advanced ALD." (PMID 41373861, 2025). "To support the CD8+ T cell expansion in aged cirrhosis we evaluated the concentration of CD8+ T cells recruiting chemokines CCL3 and CXCL10." (PMID 39656486, 2024). "The increased secretion of chemokines such as CXCL10, CCL2, CCL4, and IL-8 have been observed in both cirrhosis decompensation and ACFL." (PMID 39273468, 2024). "A previous study on cytokines in cirrhosis demonstrated that HBV- and HCV-cirrhosis affected CXCL10, CXCL8, M-CSF and TNF serum levels." (PMID 36230823, 2022). "In accordance with that publication, we found elevated levels of CXCL10, CXCL8 and M-CSF in serum of cirrhotic patients with HBV and HCV, and for the first time describe similar alterations in ALD and NAFLD cirrhosis." (PMID 36230823, 2022). "Increased CXCL-10 levels promote NK cell apoptosis, which contributes to systemic immunosuppression, and the IgG production and costimulatory functions of CD27 memory B cells are impaired in cirrhosis." (PMID 39273468, 2024). "We also found an increased CXCL10 staining in HBV infection-induced hepatic cirrhosis but not in normal liver." (PMID 32641985, 2020). "In decompensated cirrhosis, with a reduced hepatocyte mass and elevated IFN-γ levels, CXCL-10 production may be primarily driven by the production of IFNs by NPC." (PMID 28584852, 2017). "HCV-cirrhosis was characterized by a 3-fold increase in CXCL10 but not IFN-γ." (PMID 36230823, 2022). "Patients with CXCL10 rs3921 CG or CXCL11 rs4619915 AG genotypes had lower odds of significant fibrosis (LSM ≥ 7.1 kPa) [adjusted OR (aOR) = 0.56 (p = 0.008)], advanced fibrosis (LSM ≥ 9.5 kPa) [aOR = 0.55 (p = 0.013)], and cirrhosis (LSM ≥ 12.5 kPa) [aOR = 0.57 (p = 0.051)]." (PMID 28755163, 2017).
Cirrhosis (continued). "Furthermore, patients with CXCL10 rs3921 CG or CXCL11 rs4619915 AG genotypes had lower odds of significant fibrosis (LSM ≥ 7.1 kPa) [adjusted OR (aOR) = 0.56 (p = 0.008)], advanced fibrosis (LSM ≥ 9.5 kPa) [aOR = 0.55 (p = 0.013)], and cirrhosis (LSM ≥ 12.5 kPa) [aOR = 0.57 (p = 0.051)]." (PMID 28755163, 2017). "Expression of CXCL10 was increased in patients with severe AH, as well as in patients with HCV either with or without cirrhosis." (PMID 33945507, 2021). "In summary, we show that in patients with decompensated cirrhosis, nonresponders to DAA therapy displayed differences in CXCL-10 profile and NK phenotype." (PMID 28584852, 2017).
depression (28 papers, 2012 to 2026). "For example, it is possible to explore the role of genes associated with CVD such as SCN5A and CXCL10 in depression and how they affect cardiovascular function and the development of depressive symptoms." (PMID 41601490, 2026). "We found 224 upregulated and 284 downregulated genes, including genes previously found to be associated with depression such as CXCL10 (FC=+2.13) and insulin-like growth factor 2 mRNA binding protein 2 (IGF2BP2, FC=+1.88)." (PMID 27067128, 2016). "Notably, a substantial number of upregulated genes associated with depression were identified, such as Ctss, Ifitm3, H2‐K1, Vim, Bst2, Lag3, Cd74, Isg15, Gbp3, and Cxcl10." (PMID 38946585, 2024). "Elevated levels of CXCL10 have been associated with impaired cognitive performance in patients with depression, and may accelerate disease progression in RA patients." (PMID 36911710, 2023). "CXCL10, also called interferon-inducible protein (IP-10), promotes chemotaxis and modulates the inflammatory responses of cells contributing to depression." (PMID 38674048, 2024). "It has been reported that the serum levels of CXCL10 were elevated during depressive episodes, and this alteration correlated with increased depression severity." (PMID 36387880, 2022). "For this purpose, the correlation between the cytokines VEGF, CCL5, CXCL8 and CXCL10 and BMI, depression, anxiety and stress was assessed while controlling for the neuropathy." (PMID 28811623, 2017). "Furthermore, higher CXCL10 levels were observed in patients with major depressive disorders compared to healthy controls and were even significantly enhanced after 8 weeks treatment with the SSRI fluoxetine in one study." (PMID 40509339, 2025). "Similarly to manic episodes, serum levels of many inflammatory markers (CRP, TNF‐α, IL‐6, IL‐1β, sTNFR1, and CXCL10) are elevated during depressive episodes, and this alteration correlates with increased depression severity." (PMID 34590391, 2022). "Serum levels of the related CXCL10 gene were found to be related to depression." (PMID 23049769, 2012).
heart failure (28 papers, 2016 to 2025). Inability of the heart to pump blood at an adequate rate to meet tissue metabolic requirements. "At the same time, elevated levels of cTnT, cTnI, CK, CK-MB, LDH, α-HBDH, CCL2, and CXCL10—hallmarks of cardiovascular pathology—suggested inflammatory responses associated with heart failure." (PMID 40762502, 2025). "Intriguingly, serum concentration of CXCL10 is increased in the patients with advanced heart failure, suggesting that CXCL10 production is closely associated with heart failure; however, it remains to be elucidated how CXCL10 expression is regulated in the failing heart." (PMID 35542987, 2022). "Moreover, CXCL10 modulates the biological functions of endothelial cells as an anti‐angiogenic factor and is associated with the progression of heart failure." (PMID 35542987, 2022). "Our findings suggest that SGLT-2 inhibitors may reduce the risk of heart failure (HF) by modulating inflammatory biomarkers, with CXCL10 potentially playing a mediating role—accounting for approximately 18% of the association between SGLT-2 inhibition and HF risk." (PMID 38566143, 2024). "Similarly, it is also reported that circulating levels of CXCL10 is associated with heart failure." (PMID 35542987, 2022). "Key findings include the downregulation of proinflammatory genes, the identification of CXCL10 as a critical inflammatory biomarker mediating therapeutic effects, and the role of LRRTM2 in reducing heart failure risk." (PMID 40520225, 2025). "Leukemia inhibitory factors and CXCL10 (C-X-C motif chemokine 10), which is present in chromosome 4 and one of the 92 inflammatory biomarkers, were linked to SGLT2 inhibition and heart failure." (PMID 40520225, 2025). "SGLT2 inhibitors have been shown to significantly reduce the expression of CXCL10, a chemokine involved in the pathophysiology of heart failure." (PMID 40520225, 2025). "Recently, it was demonstrated that CXCL10 is a circulating inflammatory marker in patients with advanced heart failure." (PMID 35542987, 2022). "These clinical findings demonstrate that blood concentration of CXCL10 is elevated in patients with heart failure; however, the mechanisms of CXCL10 induction remain to be addressed." (PMID 35542987, 2022). "Elevated CXCL10 is one of the best biomarkers differentiating healthy and heart failure subjects in circulation; the role of elevated CXCL10 in the context of PrEP will require further study." (PMID 35967369, 2022). "CXCR3 ligands such as CXCL9 and CXCL10 are considered as biomarkers for heart failure and other cardiovascular diseases." (PMID 35251049, 2022). "CXCL10, for instance, is critical in leukocyte recruitment that occurs in heart failure, and IFNI signals downstream of STING have been reported to fuel cardiac damage in response to myocardial ischemia." (PMID 34156982, 2021). "The underlying mechanism of the vitamin D receptor agonist involvement in Treg along with the reduction of CXCL10 in patients suffering from heart failure needs to be further delineated." (PMID 34835155, 2021). "Circulating CXCL10 was found as the best indicators amongst others chemokines for differentiating healthy and heart failure patients." (PMID 33256720, 2020). "Circulating CXCL9 and CXCL10 concentrations are also elevated in patients with heart failure, but to a lesser extent than what we observed in chronic Q fever patients." (PMID 28793883, 2017). "The findings of these two studies are consistent with the idea that inflammation is involved in the pathogenesis of heart failure with CXCL10 playing a central role." (PMID 27795961, 2016). "We found that serum CXCL10 levels were increased in patients with symptomatic heart failure as indexed by NYHA classification II through IV and were positively correlated with serum levels of Th1 proinflammatory cytokines." (PMID 27795961, 2016).
heart failure (continued). "Notably, CCL2 and CXCL10 are established biomarkers of heart failure and left ventricular dysfunction (48, –, 52), aligning with the observed ZIKV-induced cardiac pathology." (PMID 40762502, 2025). "CXCL10 has been shown to influence cardiac hypertrophy and fibrosis resulting from pressure overload, along with the functional impairments that characterize heart failure." (PMID 40520225, 2025). "Notably, the beneficial effects of SGLT2 inhibitors on heart failure can be attributed to the modulation of CXCL10, making this pathway a promising therapeutic target." (PMID 40520225, 2025). "Circulating levels of CCL3 (as well as CXCL10 and CD40 ligands) were associated with heart failure." (PMID 36769452, 2023). "In addition, we observed that serum levels of CXCL10 are increased in patients with symptomatic heart failure." (PMID 29556499, 2018). "Whether a vitamin D receptor agonist or supplementation increases Treg levels and reduces CXCL10 levels in heart failure patients will need to be assessed." (PMID 27795961, 2016). "CXCL10 (IP-10, detected in the patient serum samples) is a known chemoattractant and polarizing factor for various immune cells, promoter of T cell adhesion to endothelial cells (ECs), inhibitor of angiogenesis, and a biomarker for heart failure and left ventricular dysfunction." (PMID 38776872, 2024). "Similarly, serum CXCL10 levels are higher in patients with heart failure." (PMID 35794867, 2022). "Notably, targeting of the CXCL10/CXCR3 axis in addition to cardiac inflammation may constitute a new pharmacological approach for either heart failure or CAD therapy supplementary to present drugs that typically target the sympathetic or renin-angiotensin system or platelets." (PMID 34835155, 2021). "More recently, we reported that circulating CXCL10, MIP-1α, and CD40 ligand were the best indicators for differentiating healthy and heart failure subjects." (PMID 27795961, 2016). "Additionally, they used the levels of CXCL9, CXCL10, and CXCL11 in their study to adjust the prediction in the heart failure model, finding that including CXCL9, CXCL10, and CXCL11 improved the prognosis prediction of heart failure." (PMID 39726944, 2024). "The role of CXCL10 in other forms of nonischemic heart failure with reduced ejection fraction, such as restrictive cardiomyopathy, ion channelopathies, and diabetic cardiomyopathy, awaits investigation." (PMID 27795961, 2016). "The relative importance of CXCL10 in concentric versus eccentric LV hypertrophy, as well as their progression to heart failure, is not known." (PMID 27795961, 2016).
prostate carcinoma (28 papers, 2012 to 2026). A carcinoma that arises from epithelial cells of the prostate gland. "Based on the results of this study, polymorphisms in CXCL10 A-1447G, IL-18 G-137C, and IL-18 C607A alleles were associated with an increased risk of prostate cancer." (PMID 39359425, 2024). "According to the results, the mutant alleles in polymorphisms CXCL10 A-1447G, IL-18 G-137C, and IL-18 C-607A alleles were associated with an increased chance of prostate cancer in this population." (PMID 39359425, 2024). "The current study was conducted to study the relationship between G-137C, C-607A, and A-1447G polymorphisms in the promoter of IL-18 and CXCL10 inflammatory genes with prostate cancer." (PMID 39359425, 2024). "In the present study, the presence of one mutant allele in the CXCL10 A-1447G polymorphism significantly increased the chance of prostate cancer by 4.902 times and the presence of two mutant alleles significantly increased the chance of prostate cancer by 7.174 times." (PMID 39359425, 2024). "CXCL10 plays a significant role in the tumor metastasis and immunesuppression in prostate cancer and being a tumor-associated macrophage, it also promotes tumor microenvironment creation, migration and invasion of prostate cancer cells." (PMID 36239108, 2022). "We also showed that CXCR3/CXCL10 axis plays a significant role in prostate cancer lung metastases in comparison to bone metastases." (PMID 39146303, 2024). "Several C-X-C motif (CXC) chemokines were upregulated in prostate cancer lung metastases, notably CXCL10, CXCL11, and CXCL13." (PMID 39146303, 2024). "We observed that TMPRSS2 and CXCL10, together with their often co-expressed genes, are important in the binding activity and immune responses in prostate cancer and COVID-19 infection, respectively." (PMID 36239108, 2022). "Since (R)-9b treatment not only activated T cells but also increased CXCL10 expression by cancer cells, we explored collective outcomes using human prostate cancer spheroids that we generated using CRPC-forming C4-2B cells." (PMID 36376335, 2022). "Firstly, we prepared a query for CXCL10 in this database using 5,584 samples of 5,389 prostate cancer patients from 18 studies." (PMID 36239108, 2022). "The functional importance of TMPRSS2 and CXCL10 in prostate cancer development was then determined by analyzing the frequency of genetic changes in their amino acid sequences using the cBioPortal online portal." (PMID 36239108, 2022). "In contrast, CXCL10 (a chemokine involved in NK cell chemotaxis) was observed to be diminished in DU145 cells compared to the other prostate cancer cells (∗p < 0.05)." (PMID 35465350, 2022). "To understand the possible causes of prostate cancer patients' increased vulnerability and mortality from COVID-19 infection, we focused on the two most important agents, transmembrane protease serine subtype 2 (TMPRSS2) and the C-X-C motif 10 (CXCL10)." (PMID 36239108, 2022). "Finally, we found many CD3+ and CD3−CXCL10+ cells in the few and small TLO from patients with evanescent prostate carcinoma, contrasting with the scarce and weak expression for CXCL10 in the glandular epithelium." (PMID 28567040, 2017). "Previous studies had demonstrated that the overexpression of CXCL10 in cancer or tumor cells inhibited cell proliferation of the transfected cells; for example, Nagpal studied the effects of overexpression of CXCL10 in human prostate cancer LNCaP cells." (PMID 24187661, 2013). "However, based on the increased numbers of Tbet+Th1 cells in TLO from patients with evanescent prostate carcinoma, we expected that IFNγ, produced by Th1-cells, stimulates local production of CXCL10—a chemokine that attracts effector lymphocytes to inflammatory sites." (PMID 28567040, 2017).